BOLL (boule RNA binding protein)
Description:
Probable RNA-binding protein, which may be required during spermatogenesis. May act by binding to the 3'-UTR of mRNAs and regulating their translation (By similarity).
Synonyms: BOULE
Tractability: PROTAC: ubiquitination databases record sites on it.
Gene: Protein-coding gene on chromosome 2 (197,726,879 to 197,786,762, reverse strand). Ensembl gene ENSG00000152430.
Subcellular location: Cytoplasm
Subcellular location (Human Protein Atlas): Annulus; End piece; Mid piece; Principal piece
Gene Ontology:
Molecular function: identical protein binding; protein binding; translation activator activity; nucleic acid binding; RNA binding
Biological process: meiotic cell cycle; positive regulation of translational initiation; 3'-UTR-mediated mRNA stabilization; regulation of translation
Cellular component: cytoplasm
Genetic constraint (gnomAD): Loss-of-function variants: 6 observed, 14.62 expected, observed/expected ratio (o/e) 0.41, 90% interval 0.22 to 0.81. The upper end of that interval is the gene's LOEUF score, 0.81, which puts it in group 3 of 6, group 1 being the genes least tolerant of losing a copy. Missense variants: 176 observed, 204.06 expected, observed/expected ratio (o/e) 0.86, 90% interval 0.76 to 0.98. Synonymous variants: 61 observed, 70.17 expected, observed/expected ratio (o/e) 0.87, 90% interval 0.71 to 1.08.
Homologues: Orthologues: macaque BOLL (99% identical), chimpanzee BOLL (98% identical), dog BOLL (95% identical), rabbit BOLL (94% identical), pig BOLL (93% identical), guinea pig BOLL (92% identical), mouse Boll (92% identical), rat Boll (83% identical), Caenorhabditis elegans daz-1 (31% identical), Drosophila melanogaster bol (30% identical). Paralogues in human: DAZL (31% identical), DAZ2 (28% identical), DAZ4 (28% identical), DAZ3 (27% identical), DAZ1 (27% identical).
Diseases named in the same sentence as BOLL in open-access papers:
BOLL is named in the same sentence as 12 diseases in open-access papers, as found by Europe PMC text mining. Sharing a sentence is not in itself a finding about the gene and the disease. The quoted sentences say what the papers report.
Azoospermia (6 papers, 2019 to 2023). Absence of any measurable level of sperm,whereby spermatozoa cannot be observed even after centrifugation of the semen pellet. "BOLL, an RNA binding protein, is an evolutionarily conserved member of the deleted in azoospermia gene family, which could cause spermatogenic arrest and sperm maturation failure in many species if lack of expression." (PMID 36195947, 2022). "The BOll/GAPDH mRNA ratio was assessed in different pathological phenotypes of azoospermia, and using a cut-off value of 0.5, sensitivity and specificity of 100% was achieved for SR13." (PMID 34158577, 2021). "Moreover, BOLL expression in adult dairy goat testes with complete spermatogenesis was significantly higher than that in testes with azoospermia or male intersex, which demonstrates that BOLL is crucial for male fertility." (PMID 30901845, 2019). "The formation of the SC and progression of meiosis is dependent on RNA binding proteins, of which the best characterized is DAZL (deleted in azoospermia-like) and its homologues DAZ (deleted in azoospermia) and BOLL (Bol-like) (reviewed in Refs." (PMID 37171807, 2023). "Boule homolog, RNA binding protein (BOLL), an ancestral member of the DAZ (deleted in azoospermia) gene family, is required for testicular function, maintenance, and spermatogenesis in males." (PMID 30901845, 2019). "In addition, BOULE (also called BOLL), a member via RNA-binding protein of the deleted in azoospermia (DAZ) gene family, complements the functions of DAZL and has been reported to be important for meiotic division and spermatogenesis." (PMID 34113673, 2021).
Infertility (4 papers, 2010 to 2021). "The relation of BOLL deletion or mutation with unfunctional sperm production that led to infertility has been reported in different studies." (PMID 34580317, 2021). "Numerous studies have shown that the BOLL gene plays an important role in testicular function, maintenance, and spermatogenesis and that loss of the gene may cause male dyszoospermia and infertility." (PMID 30901845, 2019). "In males, deletion or mutation of BOLL may block production of functional sperm, thereby leading to infertility." (PMID 30901845, 2019). "In the testes of infertile men, BOLL mRNA is significantly decreased and BOLL protein is completely absent compared to in healthy men." (PMID 34439962, 2021). "The downregulation of BOLL expression in male gonads is related to its methylation degree and, consequently, with meiotic arrest and infertility." (PMID 30901845, 2019). "The RNA binding protein BOLL is an ancestral member of the deleted in azoospermia (DAZ) gene family, which plays an important role in maintenance of testicular function, testicular growth, and spermatogenesis, and loss of this gene may cause male dyszoospermia and infertility." (PMID 34439962, 2021). "Expression of BOLL mRNA is significantly decreased and BOLL protein is completely lacking in the testes of infertile men, when compared to healthy men." (PMID 30901845, 2019).
lung carcinoma (2 papers, 2017 to 2019). "Aberrant DNA methylation of the BOLL promoter has been observed in patients with colorectal or lung cancers." (PMID 31100866, 2019).
bipolar disorder (1 paper, 2024). A disorder of the brain that causes unusual shifts in mood, energy, activity levels and the ability to carry out day-to-day tasks. "Genes that were associated with brain volumes, depression, and schizophrenia or bipolar disorder includedAC011997.1,AKT3,BANK1,BOLL,DCC,HSPD1,HSPE1,HSPE1-MOB4,MOB4,PLCL1,RFTN2,SF3B1, andTRPS1." (PMID 40800518, 2024).
colorectal cancer (1 paper, 2019). A primary or metastatic malignant neoplasm that affects the colon or rectum. "Increased cell proliferation and migration were observed in BOLL-transfected cells, suggesting that BOLL functioned as an oncogene in colorectal cancer." (PMID 31001336, 2019).
ICF syndrome (1 paper, 2020). "Another study found a decrease in DNA methylation in LCLs of ICF syndrome patients near genes related to germline function (BOLL, SYCP2, LDHAL6A, and NCRNA00221) and an increase in mRNA levels, concordantly with a previous report of germline gene hypomethylation in ICF syndrome patients." (PMID 31963661, 2020).
cancer (3 papers, 2011 to 2024). A tumor composed of atypical neoplastic, often pleomorphic cells that invade other tissues. "Two of the genes (KIF17 and ATP8A2) showed no methylation in either cancer or matched tissues, and eight genes (EPHA4, OVOL1, UTF1, ADAM8, BOLL, FOXE3, GUCY1A2, and ADCY5) were equally methylated in the two groups." (PMID 21625442, 2011).
BOLL also shares sentences with these, for which no sentence is quoted: tumor (2 papers); depression (1); intracranial aneurysm (1); ovarian tumors (1); schizophrenia (1).